JCHAIN (joining chain of multimeric IgA and IgM)
Diseases named in the same sentence as JCHAIN in open-access papers (continued):
Sharing a sentence is not in itself a finding about the gene and the disease.
cancer (20 papers, 2019 to 2025). A tumor composed of atypical neoplastic, often pleomorphic cells that invade other tissues. "The results of the mutation analysis showed that JCHAIN had amplification, mutation, and deep deletion in a variety of cancers, with amplification accounting for the majority." (PMID 41010015, 2025). "In most cancers, JCHAIN gene expression is closely linked to immune-related genes, immune cells, and methylation, as well as to being affected by mutations." (PMID 41010015, 2025). "Another study found that the JCHAIN expression in the peripheral blood of cancer patients was substantially linked with prognosis." (PMID 41010015, 2025). "In this study, JCHAIN was discovered to be positively linked with B cells in most malignancies, implying that JCHAIN modulates the tumour microenvironment and prevents cancer progression via B cells." (PMID 41010015, 2025). "We also examined the relationship between JCHAIN and gene mutations, methylation analysis, and immune infiltration across various cancer types, and employed single-cell and spatial transcriptomics to investigate the association between JCHAIN and the immune microenvironment in BRCA." (PMID 41010015, 2025). "The JCHAIN was shown to be positively connected with 28 lymphocytes in 30 cancer types, and JCHAIN was found to be positively correlated with CD8+ T-cells, macrophages, B cells, and Tregs by various algorithms on the TIMER3 website." (PMID 41010015, 2025). "Then, using the “Subtype” module on the TISIDB website, we examined JCHAIN expression in relation to immunological and molecular subtypes in each cancer." (PMID 41010015, 2025). "In this study, we analysed the DNA methylation status on the promoter of JCHAIN and found that JCHAIN promoter methylation was significantly different in most cancers." (PMID 41010015, 2025). "The JCHAIN was found to be negatively correlated with RNA methylation modification genes in most cancers." (PMID 41010015, 2025). "Eight genes are in the overlap of all subgroups, among them immune-related genes (DEFB1, AOC1, JCHAIN) as well as genes (215780_s_at/SET, SPP1) that were reported in the literature to be associated with different types of cancer." (PMID 34876106, 2021). "As a key immune modulator, the JCHAIN has been extensively studied in various cancers." (PMID 41010015, 2025). "Subsequent prognostic analyses demonstrated that low JCHAIN gene expression was related with a poor prognosis in most malignancies, and JCHAIN expression was found to be an independent prognostic factor for most cancers using univariate Cox regression." (PMID 41010015, 2025). "We analysed JCHAIN expression and prognosis in various cancers." (PMID 41010015, 2025). "This was followed by an in-depth study of JCHAIN expression in various cancer immune subtypes." (PMID 41010015, 2025). "JCHAIN could regulate genes and pathways that are essential for cancer cell survival and proliferation." (PMID 41153653, 2025). "Therefore, we studied the relationship between RNA methylation signature genes (including m1A, m5C, and m6A) and JCHAIN gene expression and found that JCHAIN was significantly correlated with RNA methylation signature genes in various cancers." (PMID 41010015, 2025). "We conducted a systematic examination of JCHAIN’s role in cancer and discovered that JCHAIN gene and protein expression was low in most cancers, including BRCA, COAD, LUSC, HNSC, and LIHC, as measured by pan-cancer analysis, and was also linked with immunostaging and molecular staging." (PMID 41010015, 2025). "Here, the model identified the downregulation of JCHAIN and CD5L plasma as the most powerful proteins to separate MM from 14 other cancer types." (PMID 37835457, 2023). "Genes related to B and T cell maturation (e.g. CD37, CD79B, JCHAIN, IGLL1, VPREB3, CD52), ribosomal protein genes (RPS-*, RPL-*) and cancer/stress genes (e.g. PRAME, ARHGDIB, FOS, JUN) were within the most significantly deregulated genes between clusters in those samples." (PMID 32415257, 2020).
cancer (continued). "However, the biological roles of JCHAIN and NCKAP1L in human cancer have rarely been investigated." (PMID 33329695, 2020).
tumor (20 papers, 2014 to 2025). "By contrast, ICC’s “MARCO+ tumor-associated macrophage (TAM)” pattern is accompanied by JCHAIN downregulation and suppresses T-cell infiltration." (PMID 41153653, 2025). "IHC and mIF validations further confirmed decreased JCHAIN protein expression in tumor tissues, and higher JCHAIN expression was associated with increased M1 macrophage density." (PMID 41153653, 2025). "Joining chain of multimeric IgA and IgM (JCHAIN) expression was notably reduced in tumor tissues, with low expression correlating with poorer prognosis." (PMID 41153653, 2025). "Streptococcus mongolensis extract was discovered to have an important anti-tumour impact in the treatment of HCC by employing JCHAIN as a core target." (PMID 41010015, 2025). "Tumor tissues exhibited significantly lower JCHAIN mRNA levels, a trend also observed in paired tumor-normal tissues comparisons, where tumor tissues and their corresponding normal adjacent tissues were obtained from the same patients." (PMID 41153653, 2025). "Elevated expression in most tumours predicts improved prognosis, suggesting JCHAIN possesses potential as a novel prognostic biomarker." (PMID 41010015, 2025). "Integrated bioinformatics and clinical validation revealed that reduced JCHAIN expression correlates with aggressive tumor phenotypes, immunosuppressive TME signatures, and poor survival." (PMID 41153653, 2025). "Meanwhile, JCHAIN mRNA was found to be less expressed in tumour tissues than in normal tissues by PCR experiments." (PMID 41010015, 2025). "We analysed CD14+ and JCHAIN+ spots across six samples and found that pro‐tumour pathways, including angiogenesis, extracellular matrix (ECM) receptor interaction and Vascular endothelial growth factor (VEGF) signalling, were enriched in CD14+ spots." (PMID 39187937, 2024). "One of the JCHAIN-related pathways is cell surface interactions at the vascular wall; it indicated that the role of plasmablast is closely related to tumor angiogenesis." (PMID 35812372, 2022). "Third, the tumor microenvironment (TME) contributes to JCHAIN suppression." (PMID 41153653, 2025). "Functional experiments showed that overexpression of the JCHAIN inhibited tumour migration and invasion, which may be closely related to the activation of the IL-2/STAT4 signalling pathway." (PMID 41010015, 2025). "When the expression of JCHAIN is abnormal, it might break the original immune balance and create a microenvironment that is either favorable for tumor growth or inhibitory to it." (PMID 41153653, 2025). "Further analysis across different stages (I–IV) and classifications (T1–T4 for tumor size, NO–N3 for lymph node involvement, and M0- M1 for metastasis) indicated a significant correlation between JCHAIN mRNA expression and T/M classifications in TMN staging (p < 0.05)." (PMID 41153653, 2025). "In the context of the TME, the reduced JCHAIN expression may disrupt the normal balance between the tumor and the immune/stromal components." (PMID 41153653, 2025). "The JCHAIN plays an important role in tumour immunity as an immune-related gene." (PMID 41010015, 2025). "JCHAIN might act as a signaling molecule that activates immune cells or promotes their recruitment to the tumor site." (PMID 41153653, 2025). "Moreover, the B‐cell marker MS4A1 was upregulated, and the plasma cell marker JCHAIN was downregulated in early CRC tumor." (PMID 33463049, 2021). "Consequently, JCHAIN expression is reduced in these tumours." (PMID 41010015, 2025). "The positive correlation with certain TICs, such as memory B cells and plasma cells, and the negative correlation with others, like M1 Macrophages and activated NK cells, suggest that JCHAIN may influence the delicate balance between anti-tumor and pro-tumor immune responses." (PMID 41153653, 2025). "While, the paired analysis showed that expression of IL26, IL17F, KLRB1, CD40LG, JCHAIN, and NFKBIZ were significantly lower in the tumor group, compared with normal tissues." (PMID 35902909, 2022).
tumor (continued). "The cell type-specific markers we used for cell annotation were as follows: T cell (CD3D); NK cell (KLRD1 and NKG7); plasma cell (IGKC and JCHAIN); Mast cell (KIT and TPSB2); tumour cell (CA9, NDUFA4L2 and SLC17A3); endothelium (PECAM1, PTPRB and KDR); mesangial cell (ACTA2 and PDGFRB)." (PMID 40830065, 2025). "No off-target reactivity of JCHAIN-negative heathy cell subsets was apparent, but on-target/off-tumor reactivity of JCHAIN expressing B cells revealed that Jchain TCR gene therapy would likely result in depletion of the healthy B-cell compartment in vivo." (PMID 36850001, 2023).
infection (3 papers, 2021 to 2026). The state of being infected such as from the introduction of a foreign agent such as serum, vaccine, antigenic substance or organism. "Mucosal tissues are a primary entry point for infection, and JCHAIN functions in the transport of immunoglobulins to mucosae." (PMID 34595226, 2021).
adenocarcinoma (1 paper, 2023). A common cancer characterized by the presence of malignant glandular cells. "Furthermore, TRAV4, which encodes T-cell receptor alpha variable 4, and JCHAIN, which encodes Ig J Chain, have been reported to be related to adenocarcinoma." (PMID 37762221, 2023).
inflammatory myopathy (1 paper, 2025). "Additionally, B-cell markers (MS4A1) and plasma cell markers (JCHAIN and SDC1) were significantly elevated compared to most other inflammatory myopathy groups, reaching levels akin to those seen in IBM muscle biopsies." (PMID 40568658, 2025).
JCHAIN also shares sentences with these, for which no sentence is quoted: viral infection (2 papers); acute myeloid leukemia (1); Arthralgia (1); atherosclerosis (1); autoimmune disorders (1); B-cell acute lymphoblastic leukemia (1); Cirrhosis (1); colon adenocarcinoma (1); colorectal carcinoma (1); endocervical adenocarcinoma (1); esophageal cancer (1); gastric cancer (1); glioma (1); head and neck squamous cell carcinoma (1); hematologic malignancies (1); hepatitis B (1); heroin dependence (1); hookworm infection (1); infectious disease (1); Kidney Chromophobe (1); Lung Squamous Cell Carcinoma (1); melanoma (1); myeloid neoplasm (1); non-small cell lung carcinoma (1); Obesity (1); osteoarthritis (1); periodontitis (1); polyp (1); rectum adenocarcinoma (1); sarcoma (1).
A further 5 diseases each share a sentence with JCHAIN in 1 paper.